COL6A3 (collagen type VI alpha 3 chain)
Description:
Collagen VI acts as a cell-binding protein.
Synonyms: BTHLM1; BTHLM1C; DYT27; UCMD1; UCMD1C
Tractability: Antibody: its Gene Ontology location is reachable by antibodies, with high confidence; UniProt places it where antibodies can reach, with medium confidence; UniProt predicts a signal peptide or a membrane-spanning region. PROTAC: ubiquitination databases record sites on it; its protein half-life has been measured. Other modalities: an approved drug acts on it.
Gene: Protein-coding gene on chromosome 2 (237,324,003 to 237,414,405, reverse strand). Ensembl gene ENSG00000163359.
Subcellular location: Secreted, extracellular space, extracellular matrix
Subcellular location (Human Protein Atlas): Endoplasmic reticulum; Vesicles; Predicted to be secreted
Pathways (Reactome):
Extracellular matrix organization: Assembly of collagen fibrils and other multimeric structures; Collagen biosynthesis and modifying enzymes; Collagen chain trimerization; Collagen degradation; ECM proteoglycans; Integrin cell surface interactions
Developmental Biology: NCAM1 interactions
Signal Transduction: Signaling by PDGF
Gene Ontology:
Molecular function: extracellular matrix structural constituent conferring tensile strength; serine-type endopeptidase inhibitor activity
Biological process: muscle organ development; response to glucose
Cellular component: extracellular exosome; extracellular matrix; extracellular region; extracellular vesicle; collagen type VI trimer; endoplasmic reticulum lumen; microfibril
Genetic constraint (gnomAD): Loss-of-function variants: 137 observed, 279.83 expected, observed/expected ratio (o/e) 0.49, 90% interval 0.43 to 0.56. The upper end of that interval is the gene's LOEUF score, 0.56, which puts it in group 2 of 6, group 1 being the genes least tolerant of losing a copy. Missense variants: 3,936 observed, 4,315.9 expected, observed/expected ratio (o/e) 0.91, 90% interval 0.89 to 0.94. Synonymous variants: 1,648 observed, 1,727.3 expected, observed/expected ratio (o/e) 0.95, 90% interval 0.92 to 0.99.
Gene-disease validity (ClinGen):
ClinGen rates the evidence that COL6A3 causes each of these diseases.
collagen 6-related myopathy (autosomal dominant; autosomal recessive): Definitive. A qualitative or quantitative defect of collagen 6 disorder that covers a wide spectrum of musculoskeletal phenotypes caused by dominant and recessive mutations in the three major collagen VI genes: COL6A1, COL6A2, and COL6A3.
dystonia 27 (autosomal recessive): Limited. Any dystonic disorder in which the cause of the disease is a mutation in the COL6A3 gene.
Homologues: Orthologues: chimpanzee COL6A3 (99% identical), macaque COL6A3 (97% identical), dog COL6A3 (88% identical), rat Col6a3 (83% identical), pig COL6A3 (79% identical), mouse Col6a3 (68% identical), guinea pig COL6A3 (65% identical), tropical clawed frog col6a3 (49% identical). Paralogues in human: COL6A6 (22% identical), COL6A5 (22% identical), COL12A1 (17% identical), COL14A1 (11% identical), VWA2 (6% identical), MATN2 (5% identical), MATN1 (4% identical), MATN4 (4% identical), COCH (4% identical), VIT (4% identical), MATN3 (3% identical), VWA1 (3% identical).
Diseases named in the same sentence as COL6A3 in open-access papers:
COL6A3 is named in the same sentence as 184 diseases in open-access papers, as found by Europe PMC text mining. Sharing a sentence is not in itself a finding about the gene and the disease. The quoted sentences say what the papers report.
Ullrich congenital muscular dystrophy (34 papers, 2010 to 2026). Ullrich congenital muscular dystrophy (UCMD) is characterized by early-onset, generalized and slowly progressive muscle weakness, multiple proximal joint contractures, marked hypermobility of the distal joints and normal intelligence. "Pathogenic or likely pathogenic variants were detected in 31 distinct genes, including COL6A1 and COL6A3, which are associated with Ullrich congenital muscular dystrophy." (PMID 41828661, 2026). "This study explores new design strategies to enhance ASO specificity, focusing on a common dominant mutation in COL6A3 gene associated with Ullrich congenital muscular dystrophy." (PMID 38993932, 2024). "A case of Ullrich congenital muscular dystrophy caused by two de novo pathogenic variants in cis (27 nucleotides apart) within the COL6A3 gene was recently reported." (PMID 39669119, 2024). "We evaluated the efficiency of this novel ASO design in correcting a common dominant mutation in COL6A3 gene (c.6210 + 1G>A) associated with Ullrich congenital muscular dystrophy (UCMD)." (PMID 38993932, 2024). "Mutations in COL6A1, COL6A2, and COL6A3 lead to a spectrum of collagen VI-related muscular dystrophies, ranging from the severe Ullrich congenital muscular dystrophy (UCMD) via intermediate phenotypes to the milder Bethlem muscular dystrophy (BM)." (PMID 40225172, 2023). "Reports demonstrate that COL6A3 mutations cause a wide range of disorders characterized by muscle weakness and connective tissue abnormalities, ranging from severe Ullrich congenital muscular dystrophy to mild Bethlem myopathy." (PMID 38057384, 2023). "Mutations in COL6A1, COL6A2, and COL6A3 lead to the severe Ullrich Congenital Muscular Dystrophy (UCMD) and a spectrum of disease of varying severity including the milder Bethlem muscular dystrophy." (PMID 40225172, 2023). "Mutations in COL6A3 cause a spectrum of muscle diseases, from Bethlem myopathy at the mild end to the severe Ullrich congenital muscular dystrophy." (PMID 36980840, 2023). "Deficiency of collagen type VI (Col VI) caused by mutations of COL6 genes (COL6A1, COL6A2, and COL6A3) gives rise to three main muscle disorders: Bethlem myopathy (BM), Ullrich congenital muscular dystrophy (UCMD), and myosclerosis myopathy." (PMID 33086603, 2020). "COL6A1/COL6A2/COL6A3 mutations cause severe Ullrich congenital muscular dystrophy (UCMD) and milder Bethlem myopathy, which can be inherited as autosomal dominant or recessive disorders, but collagen VI mutations can also affect the skin and tendon." (PMID 31387942, 2019). "Mutations in COL6A1, COL6A2 and COL6A3 encoding collagen VI, cause Ullrich congenital muscular dystrophy (UCMD), Bethlem myopathy (BM) and myosclerosis myopathy." (PMID 25158062, 2014). "Mutations in the COL6A1, COL6A2, and COL6A3 genes cause collagen VI-related myopathies (COL6-RM) that include Ullrich congenital muscular dystrophy (UCMD), Bethlem myopathy (BM), and myosclerosis myopathy (MM)." (PMID 37047652, 2023). "Mutations in genes encoding collagen VI (i.e., COL6A1, COL6A2, and COL6A3) have been identified as causative in Ullrich congenital muscular dystrophy (UCMD) and Bethlem myopathy (BM)." (PMID 26753503, 2016). "Deficiency of ColVI due to mutations in COL6A1, COL6A2, or COL6A3 gives rise to three main muscle disorders, Ullrich congenital muscular dystrophy (UCMD, MIM #254090), Bethlem myopathy (BM, MIM #158810), and myosclerosis myopathy (MIM #255600)." (PMID 25477819, 2014). "Mutations in COL6A1, COL6A2 and COL6A3 genes result in collagen VI myopathies: Ullrich congenital muscular dystrophy (UCMD), Bethlem myopathy (BM) and intermediate phenotypes." (PMID 22075033, 2012). "By contrast, Stickler syndrome has the most collagens (six) linked to this syndrome (COL2A1, COL9A1, COL9A2, COL9A3, COL11A1, and COL11A2), followed by Ullrich congenital muscular dystrophy, with four collagens associated (COL6A1, COL6A2, COL6A3, and COL12A1)." (PMID 37189830, 2023).
Ullrich congenital muscular dystrophy (continued). "Ullrich congenital muscular dystrophy (UCMD) is a rare disease caused by mutations in the COL6A1, COL6A2 or COL6A3 genes leading to deficiency of collagen VI in extracellular matrices (ECM)." (PMID 35925158, 2022). "Ullrich congenital muscular dystrophy (UCMD), Bethlem myopathy (BM), and myosclerosis myopathy (MM) are diseases caused by mutations in each of the three genes (COL6A1, COL6A2, and COL6A3) encoding the extracellular matrix protein collagen VI." (PMID 32053901, 2020). "Dominant-negative mutations in the genes that encode the three major α chains of collagen type VI, COL6A1, COL6A2, and COL6A3, account for more than 50% of Ullrich congenital muscular dystrophy patients and nearly all Bethlem myopathy patients." (PMID 28918041, 2017). "Ullrich congenital muscular dystrophy (UCMD) is caused by mutations in collagen VI genes (COL6A1, COL6A2 and COL6A3) and is characterised by congenital hypotonia, proximal muscle weakness and distal joint hyperlaxity." (PMID 26670220, 2015). "Mutations in the genes encoding collagen VI (COL6A1, COL6A2 and COL6A3) result in two major phenotypes: Bethlem myopathy [BM, OMIM #158810] and Ullrich congenital muscular dystrophy [UCMD, OMIM #254090]." (PMID 20302629, 2010). "Mutations in the COL6A1, COL6A2, and COL6A3 genes result in either the absence or malformation of the microfibrils, causing a spectrum of muscle disorders: Bethlem myopathy (BM, MIM 158810), Ullrich congenital muscular dystrophy (UCMD, MIM 254090), and myosclerosis myopathy (MM, MIM 255600)." (PMID 37569848, 2023). "In humans, mutations in any of the three genes coding for collagen VI (COL6A1, COL6A2, COL6A3) result in defective ECM composition and cause a wide clinical spectrum of collagen VI myopathies including Ullrich congenital muscular dystrophy (UCMD), Bethlem myopathy (BM) and myosclerosis myopathy." (PMID 23437220, 2013). "This group includes collagen VI‐related dystrophies such as Ullrich congenital muscular dystrophy (UCMD) and Bethlem myopathy (BM), caused by mutations in the COL6A1, COL6A2 and COL6A3 genes." (PMID 39523858, 2024). "Mutations in any of the three collagen 6A genes COL6A1, COL6A2 and COL6A3 result in Ullrich congenital muscular dystrophy (UCMD), Bethlem myopathy (BM) or phenotypes intermediate between UCMD and BM, characterised by a combination of distal laxity, proximal muscle weakness and joint contractures." (PMID 22075033, 2012). "Mutations of COL6 genes (COL6A1, COL6A2, and COL6A3) cause COL6-related myopathies, a group of rare inherited muscle diseases that include Bethlem myopathy (BM) and Ullrich congenital muscular dystrophy (UCMD), as well as the limb girdle and myosclerosis myopathy variants." (PMID 27656840, 2016).
Obesity (26 papers, 2010 to 2026). Accumulation of substantial excess body fat. "The C-terminal domain of COL6A3, known as the Kunitz domain, is cleaved to form endotrophin, a fragment that has been implicated in fibrosis and inflammation and in obesity-induced metabolic dysfunction." (PMID 39856218, 2025). "Two-step Mendelian randomization, combined with multiple layers of omics evidence, implicates COL6A3-derived endotrophin as a mediator of coronary artery disease risk in the context of obesity." (PMID 39856218, 2025). "Alternatively, in addition to the IGF/IGFBP/IGFALS ternary complex, MMP2 can cleave COL6A3 to generate endotrophin, which is associated with onset of obesity-related metabolic disorders." (PMID 38645061, 2024). "It has only been reported that Col6a3 is associated with cancer, muscular dystrophy, and obesity, which exhibits the possible similar roles of Prmt7." (PMID 36013373, 2022). "COL6A3 expression has been shown to be reduced in obesity, whereas weight loss achieved by caloric restriction and surgery increased COL6A3 expression in subcutaneous AT." (PMID 34445187, 2021). "In human adipose tissue, consistent with rodent models, up-regulation of COL6A3 associates positively with obesity-related inflammation, insulin resistance and metabolic dysregulation." (PMID 33214660, 2020). "Our studies have reported that MMP14 cleaves the COL6A3 chain to generate endotrophin, a bioactive peptide associated with obesity pathogenesis." (PMID 33317052, 2020). "In conclusion, we identified the homeobox factor PRRX1 as a novel transcriptional regulator associated with COL6A3 expression, providing new insight into the regulatory mechanisms of altered adipose tissue function in obesity and insulin resistance." (PMID 33214660, 2020). "Of note, although we found a significant mean increase in COL6A3 expression after fat loss, some patients showed a higher expression in obesity, suggesting some inter-individual variation." (PMID 20543949, 2010). "COL6A3 is a subunit of collagen VI trimer that has been previously implicated in a variety of phenotypes including cell senescence, ascending aorta size, and obesity." (PMID 38989470, 2024). "In a comprehensive assessment to study the role of COL6A3 in human obesity and diabetes, it was revealed that COL6A3 expression increased after weight loss and showed a negative correlation with obesity, which is in good agreement with our findings in the current study." (PMID 37252399, 2023). "Previous reports have supported a role for COL6A3 in inflammation obesity and obesity-associated insulin resistance which may lead to a higher incidence and more rapid progression of diabetes complications." (PMID 35692390, 2022). "Endotrophin, a cleavage product of collagen VIα3 (COL6A3), contributes to fibroinflammation in adipose tissue and exacerbates systemic insulin resistance in obesity." (PMID 41786973, 2026). "Discordant results regarding COL6A3 mRNA in human obesity, with higher and lower levels in subcutaneous fat, have been reported." (PMID 37884762, 2024). "COL6A3 (MIM *120,250), which encodes type IV collagen, has been associated with short stature, obesity, and brachymetaphalangia in affected individuals." (PMID 37993819, 2023). "In obesity, COL6A3 expression in SAT is higher in humans with insulin resistance than those who are sensitive to insulin." (PMID 37239083, 2023). "The down-regulation of Col6a3 mRNA upon TNF-α treatment in 3T3-L1 cells is consistent with COL6A3 down-regulation in the context of inflamed adipose tissue from people with obesity, and up-regulation after bariatric surgery and diet-induced weight loss." (PMID 33214660, 2020). "Two of these are Col6a3 and Lum that, besides their structure-related functions, have also been related with obesity development." (PMID 31620014, 2019). "We therefore further tested the hypothesis that C-terminal COL6A3 mediates the relationship between obesity and CAD using analyses from orthogonal resources." (PMID 39856218, 2025).
Obesity (continued). "Our finding that Col6a3 was significantly lower in the mPVAT from obese female vs. obese male mice suggests that female mPVAT may be relatively protected from obesity-induced stiffness." (PMID 39856754, 2025). "Here, by integrated two-step proteome-wide MR, colocalization, observational assessments, epigenomics and single-cell RNA sequencing, we identify five mediators of the effects of obesity on cardiometabolic diseases and prioritize COL6A3 as a potentially actionable therapeutic target." (PMID 39856218, 2025). "Furthermore, follow-up analyses suggested that endotrophin, the cleaved product of C-terminal COL6A3, drives the effect of obesity on CAD." (PMID 39856218, 2025). "Increased COL6A3 expression in obesity restricts fat storage in SAT, which might lead to the lipid accumulation into VAT instead." (PMID 37239083, 2023). "Furthermore, these genes showed a divergent modulation in obesity, with only COL6A3 being correlated to the degree of fibrosis, and, notably, in an inverse manner." (PMID 37174662, 2023). "One study reported that, in obese humans, COL6A3 is upregulated after weight loss and downregulated in obesity, but these fluctuations had no connection to metabolic dysfunction." (PMID 37239083, 2023). "Heterogeneity in cellular phenotypes of adipose tissue in different physiological contexts may therefore explain the variable results observed for COL6A3 expression in different cohorts and interventions of people with obesity." (PMID 33214660, 2020). "Col6a3 encodes a collagen type highly expressed in WAT that possesses an important role in adipocyte physiology and is positively correlated with the dysregulation of human adipose tissue in obesity." (PMID 31620014, 2019). "Moreover, we also performed qPCR on the eight most significantly up-regulated homeobox transcription factors, in addition to COL1A1 (most up-regulated gene) and COL6A3 (recently connected with obesity)." (PMID 20543949, 2010). "Second, MMP7 expression levels (and of COL6A3 encoding collagen VI alpha) were found to be increased in ScWAT of obese insulin resistant subjects as compared with obese-insulin sensitive subjects, suggesting an involvement of MMP7 in obesity, ECM remodeling and insulin resistance." (PMID 37445827, 2023). "However, it should also be noted that other studies have reported reduced COL6A3 mRNA expression in obesity, that COL6A3 expression was higher in small compared to large adipocytes, and that COL6A3 may prevent adipose tissue inflammation induced by MCP1." (PMID 37108048, 2023). "Given our finding that reducing levels of COL6A3 and its cleaved product endotrophin can reduce the risk of CAD without apparent adverse health outcomes, directly targeting endotrophin could be an attractive therapeutic approach that may be particularly effective in individuals with obesity." (PMID 39856218, 2025). "We observed significant upregulation of proteins like COL1A1, COL6A3, FABP4, and LEP in individuals with obesity, indicating potential roles in adipose tissue dysfunction and metabolic dysregulation." (PMID 38732002, 2024). "This analysis showed that some proteins, such as COL1A1, COL6A3, FABP4, LEP, LGALS1, and THBS4, are obesity-specific, and GDF15, LPL, MCFD2, REG1A, REG1B, and TCN2 are T2D-specific." (PMID 38732002, 2024). "HFD-induced obesity led to upregulated expression of extracellular matrix (ECM) genes (Col3a1, Col6a3, Eln, and Sparc) and downregulated expression of immunoregulatory genes (Iigp1 and Cxcl10) in these stromal subtype cells." (PMID 32785175, 2020). "Consistent with findings from the early-stages of diet-induced obesity studies, our network analysis identified increased expression of common collagen-related ECM transcripts COL1A1, COL3A1, COL16A1, COL4A4, and COL6A3." (PMID 26678390, 2015). "Although we found no study that reported a relation with CVD, COL6A3 has been associated with CVD risk factors, such as obesity, inflammation, and insulin resistance." (PMID 37079385, 2023).
Obesity (continued). "Also the omental samples (available from the 12 patients with obesity) showed positive correlations of PRRX1 and COL6A3 mRNA (SVF: p = 8.66E-5, r = 0.894; adipocytes: p = 0.263, r = 0.335, data now shown)." (PMID 33214660, 2020).